EIF5A (eukaryotic translation initiation factor 5A)
Diseases named in the same sentence as EIF5A in open-access papers (continued):
Sharing a sentence is not in itself a finding about the gene and the disease.
cancer (continued). "Furthermore, there is evidence of eIF5A being important in different diseases such as diabetes, cancer and HIV infection." (PMID 32235505, 2020). "Furthermore, since the hypusinated eIF5A is indispensable for tumour growth, as well as being closely related to the aggressiveness of cancers, the discovery of novel specific inhibitors of hypusination is highly awaited." (PMID 32235505, 2020). "Eukaryotic translation initiation factor 5A (EIF5A) promotes cancer metastasis." (PMID 30761741, 2019). "The eIF5A-1 isoform is expressed at high levels in all tissues, although the eIF5A-2 isoform is detectable only in some embryonic tissues, adult testis, central nervous system and cancer tissue." (PMID 24832488, 2014). "In most of the studies, eIF5A is overexpressed in tumours and has been linked to patient prognosis in some types of cancer, although the impact of fully hypusine-modified eIF5A in cancer biology is still unknown." (PMID 24832488, 2014). "Differential expression of the two eIF5A isoforms has been observed in different cancers." (PMID 23029619, 2012). "Aberrant expression of the two eIF5A isoforms is reported in various cancers other than HCC." (PMID 23029619, 2012). "It is found that there are different eIFs aberrantly expressed in liver tumors, the content below will focus on one eIF family member, eIF5A, which is a unique member of the protein synthesis pathway and has been reported to have an oncogenic role in cancer development." (PMID 23029619, 2012). "Similarly, compounds such as GC7, which can inhibit eIF5A hypusination may be useful in enhancing immune responses and overcoming the immunosuppressive states that are induced in cancers and in certain infections." (PMID 40510183, 2025). "EIF3B as a promising therapeutic target may have similar effects to EIF5A in cancer treatment." (PMID 33996561, 2021). "Besides, the EIF5A protein has been used to develop new drugs for the treatment of cancer." (PMID 33996561, 2021). "On the other hand, in cases when eIF5A is overexpressed, such as found in several cancers, these same signatures would have their translation efficiency increased, which could have implications for cancer progression." (PMID 33292102, 2020). "Moreover, a strong correlation exists between increased levels of eIF5A and cancer." (PMID 32605139, 2020). "For the prioritized genes EIF5A and ZNRD1, we further conducted an analysis to understand the influence of their expression on downstream genes in cancer cells." (PMID 41216857, 2025). "As a key translation factor, EIF5A, and in particular its isoform EIF5A2, is overexpressed in various cancers." (PMID 40959079, 2025). "Decreased eIF5A activity impairs mitochondrial function, which activates signalling through HRI to eIF2α phosphorylation, reducing cancer cell proliferation." (PMID 41390489, 2025). "Cancer cells have evolved RQC modulating strategies, such as resolution of elongation stalling of Myc by eIF5A or programmed frame-shifting to handle amino acid shortage." (PMID 36187485, 2022). "Consistently, previous reports indicate that EIF5A and PRMT1 promote cell proliferation in the case of several human cancers." (PMID 35450295, 2022). "Study demonstrated that accumulating evidence links eIF5A to cell proliferation, cancer progression, invasiveness, metastasis and poor clinical prognosis and the post-translational modifications of eIF-5A could be a suitable target for the potentiation of the activity of anti-cancer agents." (PMID 25380840, 2014). "EIF5A can regulate PEAK1-YAP1-TEAD signaling and cancer progression." (PMID 39802932, 2025). "Spermidine-mediated hypusination appears to be essential to most, if not all, of eIF5A’s biological functions, thus rationally emerging as a potential target for both therapy and prevention of cancer." (PMID 37653021, 2023).
cancer (continued). "In addition, these studies revealed that eIF5A, BRD9, XRCC1, CYP1A1, and CRABP2 were miR-486-3p-regulated cancer-promoting genes in NSCLC cells." (PMID 37508549, 2023). "OS remained significantly altered with differences in expression of eIF2G (p < .050) and eEF1A1 (p < .020), but not for eIF5A cancer stroma expression (p < .219) or eIF5A nuclear expression (p < .065)." (PMID 35718769, 2022). "Clinical outcomes were significantly worse for women with low levels of eIF5A nuclear expression, but not if women had high levels of eIF5A cancer stroma overexpression." (PMID 35718769, 2022). "Translation elongation factor EEF1B2 and translation initiation factor EIF5A have non-canonical functions unrelated to protein synthesis, which are reported to control cancer cell proliferation." (PMID 26894977, 2016). "Genes coding for proteins supporting cancer cells survival or proliferation such as FOXD1 or EIF5A appeared up-regulated in resistant and not in sensitive, while E-cadherin, CLDN7, MDK, PKDCC, and JAG1 were more down-regulated." (PMID 27835869, 2016). "In mammals, the main isoform, eIF5A1 (generally called eIF5A), is constitutively expressed in all cells and tissues, whereas the second isoform, eIF5A2 protein, is not normally detectable, except in certain cancer cells." (PMID 34273022, 2022). "Despite the involvement of eIF-5A in apoptotic processes in various cancer models, we could not confirm such role in GBM cells." (PMID 22927971, 2012). "Finally, inhibition of eIF5A via GC7 and reduction in PEAK1 expression, increased sensitivity of PDAC cells to the chemotherapeutic drug Gemcitabine, suggesting that this could be a potential strategy for future cancer treatments." (PMID 36511302, 2022).
tumor (65 papers, 2012 to 2025). "So far, only a few target genes associated with eIF5A hypusination have been reported in tumor cells, such RhoA and MYC." (PMID 38654332, 2024). "Two human genes encode eIF-5A, being eIF5-A1 constitutively expressed whereas eIF5-A2 is frequently found overexpressed in human tumours." (PMID 36915194, 2023). "To confirm the cell proliferative potential caused by EIF5A in vitro experiment, we designed an in situ tumour model in nude mice." (PMID 30761741, 2019). "Additionally, a higher degree of tumor stromal eIF5A hypusination was significantly associated with a more advanced tumor stage." (PMID 38689086, 2024). "LSD1 can mediate a large number of genes down-regulated by YAP/TAZ, including tumor suppressors in YAP/TAZ-activated cells, which confirms that YAP/TAZ drives cell proliferation and tumor growth through the polyamine-eIF5A oligomerization-LSD1 axis." (PMID 40568576, 2025). "In summary, the hypusinated effects of polyamine-dependent eIF5A can enhance the anti-tumor effects of CD8+ cells directly via MTP and can be restored by dietary supplementation." (PMID 40040695, 2025). "Here, the authors show that inhibiting translation elongation through eIF5A impairs mitochondrial function, slowing the proliferation of tumour cells." (PMID 41390489, 2025). "Emerging evidence indicates that dysregulated mRNA elongation, involving alterations in eEF2 activity and eIF5A expression, also contributes to tumour cell growth." (PMID 41390489, 2025). "GC7, a well-established competitive inhibitor of DHPS, has been widely used to block eIF5A hypusination and inhibit tumor growth in vitro and in vivo, including in CRC models." (PMID 41408852, 2025). "eIF5a hypusination declines as the body ages, nevertheless, it can augment the anti-tumor efficacy of CD8+ T cells lymphocytes by directly targeting mitochondrial trifunctional protein (MTP), and can be reinstated with dietary supplementation with spermidine." (PMID 40040695, 2025). "Immunohistochemistry further revealed high expression of EIF5A in the primary tumor tissue of HNSCC patients with distant metastasis." (PMID 38862693, 2024). "Both the sarco-sphere model as well as the corresponding tumor tissue harbored an in-frame EIF5A::USP6 fusion in chromosome 17, homozygous losses of CDKN2A/B and ATRK, a truncation in the NOTCH1 gene and a TCF3::SLC39A3 rearrangement." (PMID 37951844, 2024). "The tumor samples in three CRC scRNA-seq cohorts were collected to explore the potential mechanism of EIF5A in the radioresistance." (PMID 39290702, 2024). "The overexpression of EIF5A and DOHH is a hallmark of many tumor types and there are modest increases in DHPS expression in many cancer types." (PMID 39125743, 2024). "Knockdown of EIF5A significantly enhances radiation sensitivity, reducing tumor volume and increasing apoptosis." (PMID 39290702, 2024). "Currently, most researchers believe that elevated polyamine levels are necessary for transformation and tumour progression, especially through the polyamine-eIF5A-hypusination axis." (PMID 38504107, 2024). "Our findings were validated using GEO data; EIF5A expression was significantly increased in the tumor tissues of HNSCC patients with distant metastasis." (PMID 38862693, 2024). "Analysis of the GSE87211 cohort revealed overexpression of EIF5A in tumor tissues compared to normal tissues (P<0.001), with higher EIF5A expression correlating with worse OS (P<0.001) and DFS (P=0.003)." (PMID 39290702, 2024). "Activation of eIF5A results in an accumulation of cells that promote tumor cell growth and aggressiveness." (PMID 36838674, 2023).
tumor (continued). "Relevance of clinical characteristics (eIF5A expression, age, gender, pT stage, pN stage, and tumor type) and prognosis were evaluated through univariate and multivariate cox proportional regression models." (PMID 35874632, 2022). "The subunits involved in the translational machinery of OC in tumour tissue or cell lines has been reported for eIF6, eIF5A, eIF5B, eEF1 and eIF2α." (PMID 35718769, 2022). "Previous studies have also found that eIF5A expression can influence tumor progression by regulating tumor stem cell differentiation." (PMID 35725615, 2022). "The evaluation of specific subunits in OC, such as eIF5A, eIF2G and eEF1A can serve as a tool to evaluate tumour agressiveness and enable the use of this markers to further investigate and determine their potential of druggable targets." (PMID 35718769, 2022). "EIF5A expression is not only a potential marker for HCC diagnosis but also a prognostic marker since it is related to tumor stage." (PMID 34234848, 2021). "Then, a scoring system method based on the percentage of positive staining tumor cells was introduced to evaluate the immunoreactivity of EIF5A." (PMID 34234848, 2021). "The overexpression of EIF5A has a close connection with tumor, which is readily revealed in many tumors that EIF5A has been considered a possible oncogene 25,26." (PMID 34234848, 2021). "Together, these data illustrate an unprecedented mechanism, whereby the tumor-promoting properties of hypusinated EIF5A are linked to its ability to regulate MYC elongation and provide a rationale for the use of DHPS/EIF5A inhibitors in CRC therapy." (PMID 33303756, 2020). "Hypusinated eIF5A is essential for general translation elongation and termination and is recognized as a critical regulator of cell growth and tumor development." (PMID 32989218, 2020). "Our data indicate that inhibition of EIF5A hypusination reduces global levels of MYC in human and mouse cells, and causes inhibition of tumor growth." (PMID 33303756, 2020). "Although the authors did not formally demonstrate that KRas is a direct translational target of EIF5A, this report provided a mechanistic explanation for the tumor-promoting effect of EIF5A in this type of malignancy." (PMID 33303756, 2020). "We did notice a significant increase in tumor size and sensitivity of tumor cells to conventional antiproliferative drugs following depletion of eIF5A." (PMID 33188200, 2020). "Two isoforms of EIF5A exist: EIF5A1, referred to as eIF5A in this study, which is expressed universally; and eIF5A2, which is mainly present in testes, brain, and tumor cells." (PMID 33326776, 2020). "We sought to verify the expression of EIF5A in tumours through immunohistochemically stained using EIF5A antibody." (PMID 30761741, 2019). "The results showed weak expression of EIF5A in the group of Panc‐1 cells with Si‐EIF5A in tumour model." (PMID 30761741, 2019). "Collectively, these results demonstrated that EIF5A and sHH signalling pathway was sufficient and necessary for tumour growth in PC." (PMID 30761741, 2019). "To determine the effect of EIF5A and sHH signalling on PC tumour growth in vivo, we assessed orthotopic tumour formation of Panc‐1 cells with Si‐EIF5A." (PMID 30761741, 2019). "As expected, the EIF5A expression in the tumor was significantly higher in the tumors than that in the peritumor tissues via qRT-PCR (P<0.001), which could also predict CRC with the AUC of 0.818." (PMID 39290702, 2024). "Next, we tested whether targeting the glutamine-derived polyamine–hypusinated eIF5A axis in TAMs attenuates tumor growth." (PMID 38689086, 2024). "In addition, EIF5A was found to be positively correlated with stemness, and knock down of EIF5A significantly decreased the ability of tumor cells to form sphere in vitro." (PMID 39290702, 2024).
tumor (continued). "Moreover, the association between elevated eIF5A hypusination in the tumor stroma and advanced tumor stage suggests that targeting eIF5A hypusination in TAMs holds promise as a potent therapeutic approach." (PMID 38689086, 2024). "In contrast, eIF5A can also exhibit tumor suppressive activity in lymphomagenesis." (PMID 36838674, 2023). "Because hypusinated eIF5A controls translation of specific mRNAs, it is possible that a set of regulatory proteins is functional, depending on the tumor type and the microenvironment, leading to the opposite biological effect, which is cytoprotection of healthy cells." (PMID 36838674, 2023). "In addition, the downregulation of eIF5A increased the expression of Bax, cleaved caspase-3, and cyto C and reduced the expression of Bcl-2 in tumor tissues (i)." (PMID 35874632, 2022). "Although the mechanism underlying eIF5A and HIF-1α expression is yet to be elucidated, this regulation makes eIF5A an attractive therapeutic target because HIF-1α mediates the adaptive response in the hypoxic environment of tumor spheroids." (PMID 35163207, 2022). "EIF5A expression was negatively correlated with six types of tumor-infiltrating immune cells." (PMID 35651789, 2022). "eIF5A has recently been shown to operate as a “translatome remodeler” that suppresses metabolism and prevents DNA damage in acidic microenvironments, where chemo-resistant stem-like tumor cells can reside." (PMID 35736348, 2022). "Furthermore, the results of immunohistochemistry suggested that eIF5A was significantly reduced (g), and the ferroptosis marker proteins (FANCD2, SLC7A11, and HSPb1) were significantly downregulated in the tumor tissues of sh-eIF5A group mice (h)." (PMID 35874632, 2022). "Engagement of eIF5A by the acidic tumor microenvironment may confer the dormant phenotype to tumor cells that is believed to increase resistance to traditional therapies and promote metastasis long after the removal of the primary lesion." (PMID 33188200, 2020). "EIF5A expression was specifically suppressed by transfection, and subsequently the alterations of growth behaviour and resistance to anticancer treatment were tested in an orthotopic tumour model." (PMID 30761741, 2019). "Furthermore, we confirmed the correlation between EIF5A and Gem sensitivity through orthotopic tumour formation of Panc‐1 cells in vivo." (PMID 30761741, 2019). "Together, these results demonstrated that EIF5A and sHH signalling pathway may be involved in and were necessary for tumour growth in PC, which is consistent with our pre‐primary work." (PMID 30761741, 2019). "Inhibition of EIF5A and sHH signalling pathway could suppress PC cells proliferation and tumour growth." (PMID 30761741, 2019). "Alternatively, there may be functional distinctions between the role of eIF5A in tumor initiation versus maintenance or progression." (PMID 29799508, 2018). "It is possible that a combination therapy with one of these agents blocking a key step in the hypusination of eIF5A and a polyamine antagonist may show additive or synergistic anti-tumor effects." (PMID 29799508, 2018). "Moreover, hypusinated eIF5A promotes tumor growth by up-regulating MYC elongation." (PMID 40040695, 2025). "They discovered that blocking eIF5A’s function in TAMs could halt tumor growth." (PMID 38689086, 2024). "Moreover, compared with control group, the tumor tissue was loose and necrotic tumor cells could be observed in sh-eIF5A group." (PMID 35874632, 2022). "The tumor growth curve showed that eIF5A silencing could restrain tumor growth (d)." (PMID 35874632, 2022). "Besides, downregulation of eIF5A promoted tumor cell apoptosis." (PMID 35874632, 2022). "At low concentrations (1–10 μM), SPD promoted DHPS-mediated eIF5A hypusination, MYC translation, and tumor cell proliferation." (PMID 41408852, 2025).